FOXP3 (forkhead box P3)
Diseases named in the same sentence as FOXP3 in open-access papers (continued):
Sharing a sentence is not in itself a finding about the gene and the disease.
tumor (continued). "In NSCLC, Ke X and colleagues demonstrated that tumor cells might induce demethylation of the forkhead box P3 (FOXP3) promoter in CD4+ T cells, leading to an increased number and activity of Treg cells." (PMID 41303477, 2025). "The distinct roles of FOXP3 in these cell populations could have significant implications for tumor biology and immune responses." (PMID 40587482, 2025). "Yet, the durability of Foxp3-dependent gene regulatory network in mature Treg cells can be compromised in diseased tissue contexts such as the tumor microenvironment; this vulnerability can be leveraged for therapeutic disruption of intratumoral Treg cell function." (PMID 41062655, 2025). "However, the CD8+ T cell to FOXP3+ Treg ratio offers additional insight into the tumor’s immune landscape and can be a more accurate predictor of therapeutic response." (PMID 40735045, 2025). "Lastly and importantly, Stigliani and coworkers showed that high Foxp3 expression of tumor biopsies predicting a better EFS and OS, was strictly correlated with perforin (PRF1) mRNA, definitively suggesting that Foxp3 is more an indicator of activation of T effector -rather than Treg cells." (PMID 40092980, 2025). "In addition, CTLA4 was highly expressed in the CD4 + FOXP3 T03 subcluster, which only accounted for 16% of cells in tumours." (PMID 39548315, 2025). "However, we did not distinguish among CD4+ T cell subsets—such as Th1, Th2, Th17, or FOXP3+ regulatory T cells (Tregs)—each of which can exert distinct and sometimes opposing immunologic effects within the tumor microenvironment." (PMID 40805225, 2025). "Finally, our findings challenge the conventional view of FOXP3+ Tregs as uniformly immunosuppressive cell population, offering evidence for their potential anti-tumor roles in specific tumor contexts." (PMID 40806346, 2025). "FOXP3 mRNA expression levels peaking in stage III tumors and decreasing in stage IV tumors in both cohorts may be the result of high number and/or activity of FOXP3+ Tregs and other immune cells in the immune-reactive tumor microenvironment of stage III." (PMID 40806346, 2025). "Our findings suggest that FOXP3 may behave as a context-dependent marker, influenced by cellular source, localization, tumor microenvironment, and potentially its interaction with PD-L1." (PMID 40806346, 2025). "Thus, Foxp3 protein depletion selectively affects highly activated tumor-infiltrating TREG cells, while leaving TREG cells in healthy organs relatively unperturbed." (PMID 40478934, 2025). "Furthermore, S100A2+ tumor subset supported the homeostasis of FOXP3+ regulatory T cells with CD86-CD28/CTLA-4 (cytotoxic T lymphocyte-associated protein 4) interaction." (PMID 40092486, 2025). "Immunohistochemistry further detects proteins such as FOXP3 in tumor tissues, which may signal a higher recurrence potential." (PMID 40507370, 2025). "Significant tumor growth attenuation could be achieved with only partial reduction in FOXP3 mRNA in preclinical studies, indicating that AZD8701 may provide clinical antitumor activity at levels of FOXP3 reduction that do not impact self-tolerance." (PMID 39937271, 2025). "Given the critical role of these cells in mediating B7-H3-induced inhibition of anti-tumor activity in ccRCC, dual targeting of B7-H3 and FOXP3+ cells may represent a promising therapeutic avenue." (PMID 40801642, 2025). "FOXP-3 is observed in the nucleus of tumor-infiltrating lymphocytes." (PMID 40565313, 2025). "This inflammation-dependent requirement for continuous Foxp3 activity enabled induction of a selective anti-tumor immune response upon systemic Foxp3 protein depletion, without causing deleterious T cell expansion in healthy organs." (PMID 40478934, 2025). "This MP4-induced FoxP3 reduction was associated with reduced tumor growth and increased levels of tumor-infiltrating CD8 cells, indicating that MP4 may reduce tumor immune evasion by Tregs." (PMID 40034859, 2025).
tumor (continued). "However, Tregs, characterized by FOXP3 expression, suppress immune responses and contribute to tumor immune evasion by inhibiting effector T cell function." (PMID 40660400, 2025). "FOXP3+ regulatory T cells (Tregs) act as tumor suppressors, while immunohistochemical studies demonstrate that immune cells regulate both antitumor responses and tumor-promoting conditions within the TME." (PMID 40242773, 2025). "Tregs accumulate in tumors through three ways: circulating tTregs are recruited into tumor nodules; the conventional CD4+ Foxp3− (Tconv cells) are converted of into pTregs cells under the influence of tumor‐derived factors including TGF‐β; and tissue‐resident Tregs proliferate on site." (PMID 39979425, 2025). "Importantly, the role of FOXP3 varies across tumor types, highlighting the need for context-specific strategies." (PMID 41150760, 2025). "Comparing the phenotype of tumor-infiltrating lymphocytes (TILs) before engraftment to those 5 days post implantation into the mice, there is an increase in activated effector T cells and a reduction of FOXP3+ regulatory T cells (Tregs)." (PMID 40948758, 2025). "In summary, the differential prognostic performance of FoxP3+ Tregs in solid tumors may be due to differences in the biological characteristics of different tumor types or within the same tumor type." (PMID 40216744, 2025). "Moreover, we observed an inverse relationship between the degree of tumor differentiation and the expression levels of PD-1, PD-L1, FOXP3, and CD25 (P < 0.05), while a direct relationship was noted for CD4 and CD8 expression levels (P < 0.05)." (PMID 40587482, 2025). "Additionally, immunofluorescence co-staining revealed significant infiltration of CD4+Foxp3+ regulatory T cells within the tumor immune microenvironment of CNS GCTs, providing initial evidence of an immunosuppressive state in these tumors." (PMID 39958339, 2025). "However, a high density of Foxp3+ TILs in the tumor stroma indicated lower recurrence/recurrence-free survival in NSCLC patients (HR = 1.90, 1.05–2.76)." (PMID 40432130, 2025). "Additionally, it enhances the production of tumour-specific IgG by B cells, inhibits FOXP3-expressing regulatory T cells (Tregs) and suppresses angiogenesis." (PMID 40361460, 2025). "Interestingly, we observed an enrichment in FoxP3+ Treg cells with a concomitant reduction in CD8+ T cells in male tumours." (PMID 39888245, 2025). "In tumor specimens, the proportion of CD4T_FOXP3+ Tregs rose, whereas CD8T_GNLY+ cells declined." (PMID 40948762, 2025). "In contrast, our article specifically investigates the role of the FOXP3 gene, its direct implications on the immune environment, and its impact on tumor progression in ccRCC, providing a more targeted approach to understanding and treating this specific cancer type." (PMID 39883234, 2025). "Moreover, mature FOXP3+ Tregs in the tumor express CXCR6, IL21R, IL1R1, IL18R1, and, to a lesser extent, CCR8." (PMID 40164596, 2025). "The study found spatial immune heterogeneity in cSCC lesions: CD8+ T cells, co-expressing both activation (Tbet, OX40) and suppression markers (FoxP3, M2-like macrophages), dominated tumor centers, while tumor margins had a more inflammatory Th1/IL-17 profile with Tbet+ cells, granulocytes, and DCs." (PMID 40868818, 2025). "In the setting of tumor treatment in vivo, Lac could drastically inhibit the transcriptional activity of FOXP3." (PMID 39979425, 2025). "Similarly, in colon cancer, tumor-infiltrating γδTreg cells frequently display a CD39+Foxp3+ phenotype, reinforcing their immunosuppressive characteristics." (PMID 40141420, 2025). "Cytokines such as IL-1β and IL-6, secreted predominantly by tumor-associated macrophages and stromal cells, in concert with suboptimal concentrations of TME-derived TGF-β, drives Treg-to-Th17 reprogramming through Foxp3 suppression and impairment of regulatory function." (PMID 41181112, 2025). "Tregs adapt to the tumor’s high lactate and low glucose through FoxP3." (PMID 39796781, 2025).
tumor (continued). "Furthermore, the crosstalk between hyperactivated Notch3 and the classical NF-κB pathway upregulates Foxp3 expression, thereby enhancing the ability of Tregs to suppress protective anti-tumor immune responses within the tumor microenvironment (TME)." (PMID 41458964, 2025). "The origin of these FoxP3 Tregs may hold significance in terms of either aiding in tumor control or promoting tumor progression by inhibiting inflammatory processes." (PMID 39857718, 2025). "Simultaneously, mice treated with HMP1G NPs showed the most effective suppression of Treg cell populations (CD3+CD4+Foxp3+) both in the spleen and within the tumor, whereas 1‐MT and HMPG NPs treatments only slightly inhibited Treg cell populations within the tumor." (PMID 39661740, 2025). "Furthermore, FMT alleviated intestinal inflammation by upregulating the anti-inflammatory cytokine IL-10 and reduced the accumulation of immunosuppressive Foxp3+ Tregs, thereby enhancing anti-tumor immune responses and suppressing CRC progression." (PMID 40771692, 2025). "Notably, the proportion of immunosuppressive Tregs (CD4+Foxp3+), on the other hand, decreased significantly, which is beneficial for enhancing overall anti-tumor immunity." (PMID 41383334, 2025). "When assessing the activity of FOXP3 as a transcription factor based on expression of genes in its regulon, activity was enhanced around the periphery of TLSs in contact with tumor stroma." (PMID 40569674, 2025). "Specifically, this mechanism could enhance the differentiation or functional stability of FoxP3+ regulatory T cells (Tregs) within the tumor microenvironment." (PMID 40244064, 2025). "Future research should also resolve the cellular context via single-cell analyses or immunophenotyping of FOXP3+ populations during the tumor progression, particularly the distinction between FOXP3-expressing Tregs, TILs, and tumor cells, to elucidate this dynamic with greater precision." (PMID 40806346, 2025). "In the TC-TLS, the effective scores of CD8+LAG-3−PD-1−TIM-3− T cells (surrounding cells: CD8+LAG-3−PD-1+TIM-3−), CD8+PD-1−TIM-3+ T cells (surrounding cells: CD8+PD-1−TIM-3−), and CD4+FoxP3+ T cells (surrounding cells: CD4+FoxP3−) were notably higher than those in the tumour and the stroma." (PMID 39901202, 2025). "Tregs, characterized by the expression of Forkhead Box P3 (FOXP3), accumulate within the tumor bed and secrete immunosuppressive cytokines such as transforming growth factor beta (TGF-β) and interleukin-10 (IL-10), thereby inhibiting effective cytotoxic T lymphocyte (CTL) responses." (PMID 41179287, 2025). "Additionally, CXCL13 can induce the expression of forkhead box P3 (Foxp3) in Tregs, which is crucial for suppressing tumor immunity." (PMID 40692663, 2025). "VEGFR2 is predominantly expressed in FOXP3+ regulatory T cells (Tregs), promoting their recruitment to tumor sites and suppressing the activation and proliferation of effector T cells, thereby enhancing tumor immunosuppression." (PMID 40563359, 2025). "CD103+ TILs were closer to tumor nests than FOXP3+ TILs in the tumor‐stromal interface." (PMID 40621806, 2025). "Moreover, the depletion of CD4+ CD25+ FoxP3 Tregs improves the efficacy cancer immunotherapies, such as checkpoint inhibitors, enhances the immune response and prolongs the survival of tumor patients." (PMID 40216744, 2025). "Interestingly, the presence of both FAP + CAFs, T-cyts (CD8 +), T-regs (CD4 + FOXP3 +), and macrophages (CD68 +) above P75 (log-rank p = 0.016) at the tumor center was associated with worse CSS." (PMID 39751643, 2025). "The European cases were also enriched in FoxP3-positive tumor-infiltrating lymphocytes (< 0.001)." (PMID 39755998, 2025). "The CD8+FoxP3+PD-1+ presence and tumor proximity were essential for favorable outcomes." (PMID 40422521, 2025). "In NSCLC, FOXP3 promotes tumor progression through the Wnt-β-catenin signaling pathway." (PMID 39883234, 2025).
tumor (continued). "Our experimental validation of FOXP3 knockdown effects was restricted to two ccRCC cell lines (Caki-1 and 769-P), limiting the representation of ccRCC tumor heterogeneity; future studies should incorporate additional cell lines and in vivo models for comprehensive validation." (PMID 39883234, 2025). "scRNA-seq profiling of tumor-infiltrating Treg cells isolated from Foxp3AIDR26WT and Foxp3AIDR26TIR1(F74G) mice following 15 days of continuous Foxp3 degradation showed profound and widespread transcriptional alterations within tumor Treg cells visualized by UMAP." (PMID 41062655, 2025). "This negative prognostic impact is further supported by a comprehensive meta-analysis encompassing 76 studies and over 15–000 patients, which demonstrated that elevated FOXP3+ Treg infiltration correlates with significantly reduced overall survival across multiple tumor types." (PMID 41394821, 2025). "Interestingly, tumour-derived Gal-1 increased frequency of CD4+CD25+Foxp3+ Treg cells in breast cancer, leading to an immunosuppressive TME." (PMID 39780187, 2025). "Furthermore, CD8+ T cells that infiltrated the tumor bed had similar levels of RORγT and Foxp3 expression in the tumor bed of both LLC and B16-bearing mice." (PMID 40553564, 2025). "In the present study, oral butyrate intake increased Foxp3 + Tregs in the tumor tissue, as well as in the gut, which may act as an inhibitory factor for antitumor immunity." (PMID 41410712, 2025). "In contrast, FoxP3+ regulatory T lymphocytes suppress CTL-mediated anti-tumor responses." (PMID 41444555, 2025). "Pathway enrichment analyses revealed that FOXP3 is associated with the activation of oncogenic pathways, including Wnt/β-catenin and TGF-β, which may contribute to its tumor-promoting effects." (PMID 39883234, 2025). "This may relate to mechanisms driving a Foxp3+ CD8+ peripheral population identified among tumor-infiltrating T cells, as well as in alloreactive T cells from GVHD models where it is constrained by high BIM expression." (PMID 39824797, 2025). "Among tumor-secreted cytokines, CAF-S1 is significantly associated with IL-17F, IL-1β, IL-10, and IL-6, which inhibit T-cell activation; the infiltration levels of FoxP3+ Tregs tend to predict a poor prognosis in tumors." (PMID 40216744, 2025). "Conversely, Foxp3+ Tregs and Th2 cells foster tumor immune evasion." (PMID 40510347, 2025). "Lacidipine also significantly inhibited tumor‐infiltrating CD4+CD25+Foxp3+ Tregs." (PMID 39585774, 2025). "In the present study, ACVR2A-KO HCC tissues were enriched with Treg cells and insusceptible to anti-PD-1 therapy, and the combination with the MCT4 inhibitor VB124 could ameliorate the CD8/Foxp-3 ratio and attenuate tumor growth." (PMID 40139191, 2025). "To gain transcriptome-wide insights into the Foxp3-dependent gene program within intratumoral Treg cells, we performed scRNA-seq profiling of tumor-infiltrating Treg cells isolated from Foxp3AIDR26WT and Foxp3AIDR26TIR1(F74G) mice following 15 days of continuous Foxp3 degradation." (PMID 40470210, 2025). "Interestingly, following treatment with B68, there was a significant increase in the number of CD8+ cells within the tumor, while the levels of PD‐L1 and Foxp3 were significantly reduced." (PMID 39721027, 2025). "Furthermore, FOXP3+ Treg cells promote tumor progression by helping neoplastic cells escape from immunosurveillance by secreting TGF-β." (PMID 39940924, 2025). "In human cancers, Foxp3+ RORγt + IL17+ cells can be found at tumor sites." (PMID 40195474, 2025). "Additionally, the protein level of FOXP3, an important transcription factor for Tregs, was decreased in the tumour as assessed by IHC." (PMID 40830825, 2025). "Additionally, treatment with anti-PD-1 antibody promoted CD8+ T cell infiltration and enhanced the CD8/Foxp-3 cell ratio in tumor tissues derived from Mct4-KD cells." (PMID 40139191, 2025).
tumor (continued). "Thus far, many parameters like circulating tumor cells, microsatellite instability, HER2, PD-L1, and FOXP3 have been used as relevant markers to assess the tumor cell dynamics and proliferative activity of gastric malignancies." (PMID 40277747, 2025). "Additionally, several preclinical studies in mouse models demonstrated that Fc-dependent depletion of tumor-infiltrating FOXP3+ regulatory T cells (Tregs), which highly express CTLA-4, co-defines the efficacy of anti-CTLA-4 therapy." (PMID 40460830, 2025). "The data confirm that high levels of FoxP3+ Tregs within the tumor microenvironment are significantly correlated with a lack of response to immunotherapy, consistent with the well-known immunosuppressive function of Tregs that can inhibit the antitumor immune response." (PMID 40723289, 2025). "GPX4 deficiency in T cells significantly accelerated tumor growth and mitigated the accumulation and function of CD8+ T cells accompanying decreased infiltration of total CD4+ T cells and CD4+Foxp3+ regulatory T cells in comparison with the control mice." (PMID 38441967, 2024). "Similarly, CCL18 or CCL1 bind to the CCR8 receptor, which is strongly expressed on tumor-infiltrating Treg, and promote Treg proliferation and activation through Foxp3 upregulation." (PMID 39598584, 2024). "Interestingly, higher expression of these genes is related to higher CD4+, CD8+, and FOXP3+ T cells as well as with higher CD163 macrophages tumor infiltration." (PMID 38790160, 2024). "Considering tumor-infiltrating FOXP3+ Treg cells may promote the immune escape of cancer cells, our findings suggest that USP11 could serve as a potential therapeutic target for the treatment of tumors with FOXP3-induced immune evasion." (PMID 38806474, 2024). "Quantitation of the absolute numbers of Foxp3− RFP+ exTreg and Foxp3+ RFP+ Treg populations revealed a significant increase in both cell types per gram of tumor in FS120m-treated mice, reflecting a general increase in lymphocyte infiltration induced by FS120m treatment." (PMID 38995700, 2024). "In terms of survival, patients with a focal (p = 0.040) and multifocal (p = 0.033) distribution of FoxP3+ cells exhibit significantly decreased overall survival and higher risk of tumor-related death, compared with those with absent FoxP3+ cells." (PMID 38672372, 2024). "B16F10 tumor-bearing Foxp3-DTR mice were treated with Tx + ɑCD4, Tx + DT, or DT alone." (PMID 38429261, 2024). "It was thought that polymorphism, which is present in the promoter region of the FOXP3, may affect the function or quantity of Treg, which in turn leads to an immune diversion against the tumor." (PMID 39315286, 2024). "Finally, the same treatment abrogated CD4+CD25+Foxp3+ Treg percentage in the tumor, opening the space for reestablishment of active antitumor immune response." (PMID 38920557, 2024). "Besides being recruited into tumors via chemotaxis, FOXP3+ Tregs can be induced in situ in tumors by mediators released from tumor cells, TAM and MDSC." (PMID 39050547, 2024). "Forkheadbox protein 3 (Foxp3) was initially identified as a key transcription factor for Tregs that is also expressed in PDAC tumor cells (also known as cancer-Foxp3) and can upregulate the expression of C-C motif chemokine ligand 5 (CCL5) to recruit Treg cells into the tumor microenvironment." (PMID 38672552, 2024). "The expression of FoxP3 in tumor cells likely contributes to carcinogenesis." (PMID 39534095, 2024). "Furthermore, we observed that pretreatment tumor tissues from female patients had markedly lower tumor mutation and neoantigen burden, but significantly higher CD4, CD4/FOXP3, and CD4/FOXP3/PD‐L1 expression level than male patients." (PMID 38899854, 2024). "Notably, higher counts of c-FOXP3+E-Cadherin− cells correlated with poorer prognosis, lower tumor differentiation, lymph node metastasis, and vascular invasion in pancreatic ductal adenocarcinoma (PDAC)." (PMID 38047300, 2024).